CD4 (CD4 molecule)
Diseases named in the same sentence as CD4 in open-access papers (continued):
Sharing a sentence is not in itself a finding about the gene and the disease.
colitis (continued). "In summary, our findings provide evidence showing that mSjci could attenuate DSS-induced colitis in mice by inhibiting the production of IFN-γ, promoting the expression of IL-10 and enhancing the population of CD4+CD25+ Treg cells." (PMID 33469451, 2020). "Under the germ-free environment, the CD4-Cre+/TgMettl14FL/FL conditional knockout mice did not develop colitis as evidenced by normal colonic weight-to-length ratio and normal cytokine expression profile." (PMID 32634481, 2020). "Despite Plac8’s regulation of IFNγ production by CD4 T cells in vitro, Plac8 ablation did not apparently alter T cell effector function in a T cell transfer model of colitis." (PMID 32639988, 2020). "Importantly, and of high translational and clinical relevance, treatment with oligonucleotides inhibiting the CD39-AS RNA ameliorates the course of TNBS colitis in NOD/scid/gamma mice, adoptively transferred with antisense+ human CD4 cells." (PMID 33208731, 2020). "The upregulation of CD4+ and B cells in the MLN may contribute to gut homeostasis and attenuation of colitis while interacting with Treg cells." (PMID 32824269, 2020). "While Plac8 significantly suppressed IFNγ production in IL-12 stimulated CD4 T cells in vitro, this phenotype was not captured in either a T cell transfer model of colitis or following Citrobacter rodentium infection." (PMID 32639988, 2020). "Similarly, exosomes secreted by dendritic cells treated with IL-10 inhibit colitis development in 2,4,6 trinitrobenzene sulfonic acid (TNBS)-treated rats by stimulating CD4+ CD25+ Treg cells." (PMID 32365813, 2020). "In mice, the positive role of nicotine in oxazolone colitis has been related to increased colonic regulatory T cells and decreased Th17 cells and its aggravating effect in TNBS colitis to increased Th17 cells among colonic CD4 T cells." (PMID 32153570, 2020). "The frequency of CD4+CD25+Foxp3+ Tregs was reduced in the experimental colitis model, however the administration of QCHS (3, 6 and 12 g/kg) or SASP markedly upregulated this percentage in the colitis model mice." (PMID 32967687, 2020). "This suggests that lower numbers of NCOR1-deficient CD4+ T cells upon transfer might not be the primary cause for the absence of inflammation, although we cannot rule out that this, together with a disease-protective cytokine expression pattern, contributes to the attenuated colitis pathology." (PMID 32318068, 2020). "To explore whether repeated administration of DSS also has systemic effects, we examined Th1, Th2, Th17 and CD4+Foxp3+ Tregs in blood and MLNs in animals with acute or chronic DSS colitis." (PMID 31296924, 2019). "As expected, the ATP production of BBR-treated colitis LP CD4+ T cells was significantly decreased relative to that of non-BBR-treated colitis LP CD4+ T cells." (PMID 31417110, 2019). "We and others recently described the importance of IL-10R signaling in macrophages in the prevention of colitis, with Il10rb−/−Rag1−/− mice but not Rag1−/− mice developing colitis upon reconstitution with WT CD4+ T cells." (PMID 30796216, 2019). "The frequency of IFN-γ-producing CD4+ T cells in BBR-treated colitis LP CD4+ T cells was significantly lower than in non-BBR-treated colitis LP CD4+ T cells." (PMID 31417110, 2019). "Patients who developed ipilimumab-induced colitis had significantly higher numbers of CD4+ T-cells but lower levels of IL-6, IL-8, and sCD25 at baseline compared to those without colitis." (PMID 30887236, 2019). "We next asked if the reduction of Stat1−/− T cells was dependent on colonic inflammation by transferring unfractionated WT or Stat1−/− CD4+ T cells into Rag1−/− mice, a strain that does not develop colitis when reconstituted with unfractionated WT T cells." (PMID 30796216, 2019). "In addition, GC-treated murine bone marrow monocytes also inhibited anti-CD3/CD28-induced proliferation of CD4+ and CD8+ T-cells in vitro and inhibited CD4+ T-cell-induced colitis in a therapeutic setting." (PMID 31507614, 2019).
colitis (continued). "These mice produce no mature T cells or B cells and develop colitis upon transfer of Treg cell-depleted CD4+Foxp3−CD25−CD45RBhigh Tcon cells (WT-Tcon only)." (PMID 30936873, 2019). "While in this latter model, colitis was not due to CD4 T cell priming as DCs lacked MHCII, in DC-LMP1/CD40-mice, MHCII is reduced but not absent." (PMID 30653608, 2019). "Colitis was also documented in patient No. 9, whose CD4 lymphocyte count reached only 252 per μL of blood." (PMID 31690039, 2019). "Our results are in contrast with this model since in our hands CD4 T cell transfer colitis is induced even in the absence of IFNγ." (PMID 29416538, 2018). "Collectively, our data suggest that the expression of WASP in macrophages but not in DC is critical for the regulation of Th17/Th1-driven colitis after CD4+ T-cell transfer." (PMID 29725003, 2018). "We previously reported that the expansion of CD3+CD4+LAP+ cells in mice is dependent on the presence of microbiota, and showed that probiotic administration increases the percentage of LP CD3+CD4+LAP+ cells and protects mice from TNBS-induced colitis." (PMID 30425718, 2018). "ETBF triggers colitis and strongly induces colonic tumors in multiple intestinal neoplasia (MIN) by Stat3 activation with colitis characterized by a selective T helper type 17 (Th17) response distributed between CD4+ T cell receptor-α/ β (TCR α/ β)+ and CD4/8-TCRγ/ δ+ T cells." (PMID 29707157, 2018). "While we find that IFNγ drives acute intestinal inflammation in the anti-CD40 colitis model in an innate lymphoid cell (ILC)-dependent manner, IFNγ secreted by both transferred CD4 T cells and/or cells of the lymphopenic Rag1−/− recipient mice was dispensable for CD4 T cell-mediated colitis." (PMID 29416538, 2018). "Indeed, indiscriminate inhibition of COX enzymatic activity with piroxicam accelerates colitis in both IL10−/− mice and during transfer of CD4+ cells from IL10−/− mice into Rag1/− mice." (PMID 30619314, 2018). "Colitis development in animals lacking WASP is mediated by CD4+ T cells and facilitated by innate immune cells." (PMID 30410494, 2018). "Nonetheless, absence of ILC3 exacerbated histopathological signs of colitis, arguing for a non-redundant and time-specific function of ILC3 in the CD4 T cell transfer colitis model." (PMID 29948108, 2018). "The differential conversion into IL17A-producing CD4 T cells, however, did not affect the severity, or the kinetics of colitis induction (data not shown)." (PMID 29416538, 2018). "Similarly, in line with previous reports, the percentage of CD4+LAP+ Tregs was significantly higher in involved tissue from patients with extensive colitis and left-sided colitis than in controls." (PMID 30425718, 2018). "Increased IFN-γ production by B cells lacking GILZ skewed wild-type (WT) CD4+ T lymphocytes toward a Th1 phenotype, increased IFN-γ production, and enhanced susceptibility to experimental colitis in mice." (PMID 30083167, 2018). "Since CD4 T cell-induced colitis develops in the absence of IFNγ, we thus assessed the pro-inflammatory cytokine profile of colitogenic CD4 T cells in the presence or absence of IFNγ." (PMID 29416538, 2018). "The differential mode of CD4 T cell priming may thus explain some of the observed discrepancies with regard to the role of IFNγ and/or IL17 in colitis induction." (PMID 29416538, 2018). "In our piroxicam-accelerated colitis study, where colitis symptoms are more acute and not directly driven by CD4 T cells, we did not observe any protective effect of IL-21 neutralization." (PMID 29849593, 2018). "We demonstrate that Alpk1-deficient mice infected with a pathobiont Helicobacter hepaticus (Hh) develop an unusually potent Th1 CD4+ T-cell response and exacerbated colitis in the absence of IL-10 signalling." (PMID 30228258, 2018). "At present, alpinetin-enhanced expression of miR-302 in colons of colitis mice and CD4+ T cells, but not miR-21, miR-155, miR-31, miR-490, and miR-148a." (PMID 30166541, 2018).
colitis (continued). "CD4+ T cells lacking CD69 expression were hindered in their ability to mature into Tregs (Foxp3+) leading to accelerated colitis." (PMID 28428788, 2017). "In addition, the early apoptosis of splenic CD4+ and CD8+ T cells in colitis mice were also significantly increased." (PMID 28824631, 2017). "In a T cell transfer model of colitis, Ccdc88b mutant CD4+ T cells do not induce colitis in immunocompromised hosts." (PMID 29030607, 2017). "To further elucidate the potential mechanism by which H. pylori attenuates the severity of TNBS-induced colitis, we treated mice with NCTC11639 after administration of TNBS enema, then isolated CD4+ T in murine colonic mucosa and finally determined the levels of Th17 and Th2 cells by FCM." (PMID 29088747, 2017). "The research has demonstrated that the administration of H. diminuta-pulsed (HD)-DCs can significantly ameliorate the severity and reduce the mortality of DSS-induced colitis, with an enhanced TH2 response and expression of TH2 cytokines such as IL-10, which is produced mainly by CD4+ T cells." (PMID 29163443, 2017). "As Bcl-3TOE CD4+ T cells failed to mediate colitis, we assessed the proliferative capacity of these cells, as it was shown that the transfer of naive T cells into lymphopenic mice initiates their homeostatic proliferation." (PMID 28452361, 2017). "We also showed that there was a dramatic induction of TH17 and TH1/TH17 immune responses in the early phase of colitis development in the transgenic mice, with much greater accumulation of IL-17-producing and INF-γ- and IL-17-producing CD4+ T cells in the lamina propria." (PMID 27271344, 2016). "By adoptive transfer of CD45RBhi CD4+ T-cells into Rag−/− or SLAMF1−/−Rag−/− mice, we found that only SLAMF1 expression by innate cells, and not T-cells, is required for the full induction of experimental colitis." (PMID 26834746, 2016). "Moreover, approximately 90% (CD4+) and 30% (CD8+) of tissue-infiltrating T-cells in colitis were identified as CCR9+ effector lymphocytes, compared to <10% of T-cells being CCR9+ in normal colon." (PMID 26873648, 2016). "For that, we adoptively transferred Rag2−/− mice with two different doses of CD25+ cell-depleted splenocytes (20 × 106 and 40 × 106 cells, containing about 3 and 6 × 106 mature CD4+CD25− T cells, respectively) and the clinical and histological signs of colitis were monitored." (PMID 27353032, 2016). "In a bone marrow chimera and CD4+CD45RBhigh T cell transfer model, lack of PGRN signaling in CD4+ T cells also exacerbated experimental colitis." (PMID 27428882, 2016). "Noteworthy, it was reported that augmentation of the inoculated naïve purified T cell pool (up to 10 × 106 Treg-depleted CD4+CD45RBhi cells) does not lead to colitis prevention." (PMID 27353032, 2016). "The results showed that the CD4+ T cells from the colitis group markedly proliferated, but not in those stimulated with BSA, indicating that OVA-specific CD4+ T cells were induced in the colon." (PMID 27604348, 2016). "Similarly, DSS colitis in NM IIA cKO mice was accompanied by a more pronounced mucosal recruitment of macrophages and CD4-positive T lymphocytes." (PMID 27063635, 2016). "Lately, an inducible colitis-associated glycome (CAG), which contains an immature (nonsialylated) core-1 O-glycan expressed by CD4+ T cells, was identified as a ligand of galectin-4 under intestinal inflammatory conditions." (PMID 27017379, 2016). "The findings demonstrate that (i) Ab-mediated IL-10 neutralization leads to progressive colitis with a reduction in Foxp3+ regulatory T cells and increased numbers of CD8+CD44+ memory T cells as well as activated CD4+CD69+ and CD8+CD69+ T cells in uninfected mice." (PMID 27611574, 2016). "Why the CD4+CD25+FoxP3+ regulatory T cells, despite increased frequency, fail to control the development of colitis has been a forum for speculations." (PMID 24414342, 2015).
colitis (continued). "Interestingly, CD4+GITR+ T cells prevent wasting disease and colitis independently of CD25 expression." (PMID 25961057, 2015). "CB-17 SCID mice injected with CD4+ CD25− T cells and treated with PBS had severe colitis." (PMID 26024301, 2015). "Inflammatory E-cadherin + DCs from the CD4+ CD45RBhigh T cell model demonstrate a potent ability to induce T cell-mediated colitis with Th17 responses; the effect on Treg cells was not significant with E-cadherin- DCs." (PMID 25651850, 2015). "In a T cell transfer model of colitis, Tpl2 ablation within the transferred T cell population reduced the proportion of CD4 T cells expressing IFNγ without altering IL-17 expression." (PMID 25781948, 2015). "NHE3 mRNA expression levels were either unaltered compared to noninflamed tissue or even increased, as in the Rag2−/− CD4+ CD45RBhigh transfer colitis model." (PMID 25271043, 2015). "In a murine T cell transfer model of colitis, transfer of Tpl2−/− T cells resulted in reduced proportions of CD4 T cells expressing IFNγ, but not IL-17A, compared to that induced by wild type T cells." (PMID 25781948, 2015). "Although colonization of wild-type C57BL/6J mice with H. hepaticus does not result in inflammation or disease, H. hepaticus induces colitis in IL10−/− or SCID/Rag2−/− hosts that received naïve CD4+CD45RBhigh T cells." (PMID 25944983, 2015). "Colitis induction in this model is only observed in the absence of Treg cells allowing for robust CD4+ T cell effector responses." (PMID 25944983, 2015). "The results suggest that ERCs may have regulatory functions on the cell populations of splenic CD3+CD25+ active T cells, CD3+CD8+ T cells, CD4+CD25+ Foxp3+ Tregs and CD11c+MHC-II+ DCs in the colitis mice." (PMID 25475342, 2014). "The RAG-2−/− LP CD4+ mice showed almost no CD3+CD4+ T cell infiltration in the liver, but did exhibit severe colitis with marked infiltrations of CD3+CD4+ T cells in the colon." (PMID 24392145, 2014). "This view is supported by the fact that IL-2 and IL-2-receptor knockout mice develop spontaneous colitis, which is thought to be due to the absence of CD4+CD25+ T regulatory cells (Treg), dependent on the presence of IL-2 for their suppressive function." (PMID 25505551, 2014). "Furthermore, it has been recently reported that a novel subset of helper CD4+ T cells producing IL-17A, namely Th17 cells, is also involved in progression of DSS-induced colitis." (PMID 24686517, 2014). "Immunodeficient mice that are adoptively transferred with Treg-depleted naïve CD4+ T cells develop spontaneous colitis; in contrast, mice transferred naïve CD4+ T cells combined with Treg cells do not develop colitis." (PMID 24787575, 2014). "Antigen-presentation in the absence of costimulatory molecules has been proposed to limit CD4+ T cell responses, which is consistent with the finding that IECs are not bona fide professional APCs capable of promoting severe colitis in vivo." (PMID 24489792, 2014). "Our efforts in the study of pathogenesis of IBD have shown that TNF is expressed mainly by F4/80+ macrophages rather than CD4+ T cells in the DSS colitis model." (PMID 24520376, 2014). "Ex vivo retroviral gene transfer of CD4+ T cells with IL-10 did not have any therapeutic benefit in acute colitis of immunocompetent mice, though it did prevent induction of colitis in a transfer colitis model using immunodeficient mice." (PMID 24712338, 2014). "Recipient mice repopulated with CD4+CD45RBLo T cells or total CD4+ T lymphocytes do not develop colitis, despite their ability to colonize the host gut." (PMID 24616886, 2014). "CD4+ T cells of the CD45RBhi type are known to induce colitis in lymphopenic mice most likely due to the absence of regulatory T cells in this lymphocyte population." (PMID 24728142, 2014). "Taken together, these data show that in the absence of CXCR3, the migration of CD4+ T cells and neutrophils to the colon is impaired during colitis." (PMID 24992040, 2014).
colitis (continued). "In antigen specific colitis model OT-II×CD69−/− CD4 T cells accumulated in cLP with or without antigen presence showing that this effect is only CD69-dependend." (PMID 23776480, 2013). "The technique can also be modified to target other immune cells, provided for example, with non-depleting 111In-labeled anti-CD4 antibodies to track CD4+ T cells, as in a murine model of colitis." (PMID 23052208, 2013). "They found that transferring CBir1-specific CD4+ T cells to SCID mice led to the development of colitis, while CD4+ T cells with a normal repertoire of TCRs did not, indicating that antigen specificity is of importance in CD4+ T cell-mediated colitis." (PMID 23936123, 2013). "Antigen-specific transfer colitis model was established to study the inflammatory response of CD4 T cells in the presence or absence of specific antigen in intestinal lumen." (PMID 23776480, 2013). "The DSS-induced colitis was restored by adoptive transfer of WT CD4 T cells, but not CD69-deficient CD4 T cells, to the CD69 KO mice." (PMID 23785429, 2013). "In order to determine whether CXCR6 expression on CD4+ T cells relates to an effector function, we performed intracellular cytokine staining on SP, MLN and colonic LP cells from colitis model mice at 8 week post-transfer." (PMID 23840334, 2013). "Although functionally active in CD4+ T cells, the deletion of Nod2 did not impair the induction and the prevention of colitis in the T cell transfer model." (PMID 24324812, 2013). "CD4+CD25+LAP+ T cells have been shown to participate in the control of intestinal inflammation in experimental models of colitis and CD4+LAP+ T cells, either expressing CD25 or not, have recently been reported as a distinct subset of T cells." (PMID 22400037, 2012). "The GMP-mediated aggravation of colitis correlated with a significant increase of CD11b+Gr1hi cells in the spleen (data not shown) and colon compared to mice that had only received naive T cells and PBS, whereas percentages of CD4+ T cells were unchanged." (PMID 23200826, 2012). "Oral B. breve administration ameliorated colitis in immunocompromised mice given naïve CD4+ T cells from wild-type mice, but not Il10−/− mice." (PMID 22693446, 2012). "Similarly, about 20-25% of those with idiopathic CD4+ lymphocytopenia develop an autoimmune problem such as SLE, antiphospholipid syndrome, Grave's disease, colitis, thyroiditis and vitiligo." (PMID 21914180, 2011). "Further, in the CD45RBhi CD4+ T cell transfer model of colitis, IL-17A mediated protection, rather than inducing inflammation." (PMID 21060867, 2010). "In contrast, transfer of the reciprocal CD4+CD45RB−/low population not only failed to induce colitis, but also prevented it." (PMID 18612428, 2008). "While TNF-α produced by CD4+ T cells is neither sufficient nor required for the induction of murine colitis, its production by Ag-presenting cells is essential for the histopathological and clinical signs of colitis." (PMID 18533024, 2008). "While the cellular mechanism(s) and response(s) mediating Mycobacteria-enhanced IBD have not been entirely demonstrated, recently we showed that colitis in IL-10-/- mice was driven in part by 85B Ag-specific CD4+ T cell responses." (PMID 18533024, 2008). "However, how CD4+ TH17 cells maintain the tissue integrity and mediate protection against DSS-induced colitis and tissue damage remains largely unknown." (PMID 40749055, 2025). "Given the significant impact of Egr-1 in CD4+ T cells for EAE and colitis treatment, it is plausible that Egr-1 could represent a potential curative target for various self-antigen reactive diseases, warranting further investigation into its clinical applications." (PMID 40235598, 2025). "The initial CD4+ T cells from spleen wild-type mice were transferred to RAG1−/− mice to establish a T cell metastatic colitis model;Rectal application of TNBS for 2 days to establish acute TNBS colitis;Mice were given DSS in drinking water for 7 days to induce colitis." (PMID 40529369, 2025).